LILRB5 (leukocyte immunoglobulin like receptor B5)
Description:
May act as receptor for class I MHC antigens.
Synonyms: LIR-8; CD85c; LIR8
Tractability: Antibody: UniProt predicts a signal peptide or a membrane-spanning region; its Gene Ontology location is reachable by antibodies, with medium confidence.
Gene: Protein-coding gene on chromosome 19 (54,249,421 to 54,257,339, reverse strand). Ensembl gene ENSG00000105609.
Subcellular location: Membrane
Pathways (Reactome):
Immune System: Immunoregulatory interactions between a Lymphoid and a non-Lymphoid cell
Gene Ontology:
Molecular function: inhibitory MHC class I receptor activity; transmembrane signaling receptor activity
Biological process: cell surface receptor signaling pathway; cytokine-mediated signaling pathway; defense response; immune response-inhibiting cell surface receptor signaling pathway
Cellular component: plasma membrane; membrane
Genetic constraint (gnomAD): Loss-of-function variants: 61 observed, 66.18 expected, observed/expected ratio (o/e) 0.92, 90% interval 0.75 to 1.14. The upper end of that interval is the gene's LOEUF score, 1.14, which puts it in group 5 of 6, group 1 being the genes least tolerant of losing a copy. Missense variants: 771 observed, 761.24 expected, observed/expected ratio (o/e) 1.01, 90% interval 0.95 to 1.08. Synonymous variants: 356 observed, 319.57 expected, observed/expected ratio (o/e) 1.11, 90% interval 1.02 to 1.22.
Homologues: Orthologues: chimpanzee LILRB5 (87% identical), macaque LILRB5 (87% identical), rat Pirb (49% identical), rat Lilrb3 (42% identical), mouse Pira12 (40% identical), mouse Pira13 (40% identical), mouse Pira2 (40% identical), mouse Pirb (40% identical), mouse Pira1 (40% identical), mouse Lilra6 (39% identical), rat LOC134485274 (39% identical), rat Lilrb2 (32% identical), and 3 more. Paralogues in human: LILRB2 (68% identical), LILRB1 (68% identical), LILRB3 (67% identical), LILRA6 (53% identical), LILRA2 (49% identical), LILRA4 (49% identical), LILRA1 (48% identical), LILRB4 (41% identical), LILRA5 (26% identical), KIR3DL1 (25% identical), KIR3DL2 (25% identical), KIR3DL3 (24% identical), and 13 more.
Diseases named in the same sentence as LILRB5 in open-access papers:
LILRB5 is named in the same sentence as 9 diseases in open-access papers, as found by Europe PMC text mining. Sharing a sentence is not in itself a finding about the gene and the disease. The quoted sentences say what the papers report.
Myalgia (3 papers, 2017 to 2023). "The LILRB5 Asp247Gly genotype has been identified as being associated with statin intolerance and statin-induced myalgia." (PMID 36998609, 2023). "Previous studies have shown that CK levels were associated with LILRB5 variant and with all definitions of intolerance, including diagnoses of myalgia, making it a potential confounder." (PMID 29020356, 2017). "In the JUPITER trial, LILRB5 Asp247Gly had a statistically significant effect on development of myalgia." (PMID 29020356, 2017). "The JUPITER trial allowed us to examine the association of the LILRB5 Asp247Gly variant in the presence and absence of statins, revealing that homozygosity of Asp247 is associated with increased odds of myalgia regardless of statin allocation." (PMID 29020356, 2017).
hepatocellular carcinoma (2 papers, 2022 to 2023). A malignant tumor that arises from hepatocytes. "LILRB5 mRNA has been detected in NK cells, with NK cells from hepatocellular cancer patients blood expressing higher levels of LILRB5 than those from healthy donors." (PMID 38022598, 2023). "LILRB5 expressed in a variety of immune cells from both peripheral blood and the microenvironment in hepatocellular carcinoma patients." (PMID 36054420, 2022).
lepromatous leprosy (1 paper, 2016). A chronic communicable infection which is a principal or polar form of leprosy. "However, LILRA3 together with LILRB5 and LILRB3 were found to be over expressed in lesions of patients with lepromatous leprosy, where their overexpression was thought to correspond to an ineffective immune response." (PMID 26908331, 2016).
liver cancer (1 paper, 2022). An epithelial or non-epithelial malignant neoplasm that arises from the liver. "Our results showed that LILRB2 and LILRB5 expression was positively associated with OS and DSS and that the mRNA expression of all LILRB family members was significantly positively correlated with RFS and PFS in liver cancer patients." (PMID 35321724, 2022). "Our study revealed that the mRNA expression of LILRB1, LILRB2, LILRB3, and LILRB5 was downregulated, while compared with normal tissues, the mRNA expression of LILRB4 was upregulated in liver cancer tissues." (PMID 35321724, 2022).
Takayasu arteritis (1 paper, 2024). A rare inflammatory large-vessel vasculitis primarily affecting the aorta and its major branches, but also other large vessels, causing stenosis, occlusion, or aneurysm. "Genome-wide association studies have revealed several associations with the LILR genomic region, such as serum levels of creatine kinase and lactate dehydrogenase (LILRB5), prostate cancer (LILRA3), and Takayasu arteritis (LILRB3/LILRA3)." (PMID 38807600, 2024).
cancer (2 papers, 2015 to 2025). A tumor composed of atypical neoplastic, often pleomorphic cells that invade other tissues. "Deletion of the CST3 gene, which encodes cystatin C, in host mice and tumor cells impaired tumor growth, whereas its overexpression accelerated cancer progression in LILRB2 and LILRB5 transgenic mice." (PMID 41233352, 2025). "Moreover, CST3 expression was significantly positively correlated with the expression of LILRB2 or LILRB5, particularly LILRB2, in most of these cancer types, although these observed Spearman’s rho values were within the range typically considered weak correlations." (PMID 41233352, 2025).
myopathy (2 papers, 2019 to 2025). A disease of the muscle in which the muscle fibers do not function properly. "A genetic variant in the LILRB5 gene (rs12975366>C) is linked to elevated muscle injury markers (CK, LDH) and increased reporting of statin‐induced myopathy." (PMID 40521636, 2025). "The immune system is implicated in both conventional statin intolerance/myotoxicity via LILRB5 rs12975366, and a strong association exists between HLA-DRB1*11:01 and anti-HMGCR positive myopathy." (PMID 31861911, 2019).
tumor (2 papers, 2020 to 2025). "Simultaneously, oligomeric cystatin C binds to the inhibitory receptors LILRB2 and LILRB5 on myeloid cells, thereby increasing their immunosuppressive activity and contributing to tumor progression." (PMID 41233352, 2025). "Interestingly, FOLR2, CD163, LILRB5, CD209 and C1QC were identified as genes of the “anti-inflammatory gene set”, whose expression is also seen in tissue-resident macrophages and tumor-associated macrophages." (PMID 32532019, 2020). "Here, we establish a direct link between oligomeric cystatin C—a cysteine cathepsin inhibitor and a well-characterized amyloidogenic protein—within the tumor microenvironment and the immune inhibitory receptors LILRB2 and LILRB5 on myeloid cells." (PMID 41233352, 2025). "Our findings provide a potential mechanistic explanation for this phenomenon: amyloid proteins activate LILRB2 and LILRB5 inhibitory receptors on myeloid cells, establishing an immunosuppressive TME that supports tumor growth and metastasis." (PMID 41233352, 2025).
infection (1 paper, 2016). The state of being infected such as from the introduction of a foreign agent such as serum, vaccine, antigenic substance or organism. "Finding LILRB5 upregulated following exposure to mycobacterium species led us to hypothesise that this receptor may have a more pertinent role in infection." (PMID 26908331, 2016). "Our results demonstrated signalling from LILRA1 and LILRB5, indicating again a potential role for LILBR5 during infection." (PMID 26908331, 2016).